TMEM45B (transmembrane protein 45B)
Description:
Plays a role in innate immunity. Mechanistically, promotes alphaviruses RNA degradation by interacting with the viral polymerase nsP4 and the mRNA-capping enzyme nsP1 and thereby interfering with the interaction between viral RNA and nsP1. Essential for inflammation- and tissue injury-induced mechanical pain hypersensitivity (By similarity).
Synonyms: BC016153; FLJ40787
Tractability: Antibody: UniProt places it where antibodies can reach, with high confidence; UniProt predicts a signal peptide or a membrane-spanning region.
Gene: Protein-coding gene on chromosome 11 (129,815,791 to 129,861,265, forward strand). Ensembl gene ENSG00000151715.
Subcellular location: Endosome membrane; Lysosome membrane; Golgi apparatus, trans-Golgi network membrane
Subcellular location (Human Protein Atlas): Nucleoplasm
Gene Ontology:
Molecular function: protein binding
Biological process: response to pain
Cellular component: endosome membrane; lysosomal membrane; trans-Golgi network; Golgi apparatus
Genetic constraint (gnomAD): Loss-of-function variants: 30 observed, 28.11 expected, observed/expected ratio (o/e) 1.07, 90% interval 0.8 to 1.45. The upper end of that interval is the gene's LOEUF score, 1.45, which puts it in group 5 of 6, group 1 being the genes least tolerant of losing a copy. Missense variants: 344 observed, 342.12 expected, observed/expected ratio (o/e) 1.01, 90% interval 0.92 to 1.1. Synonymous variants: 141 observed, 134.02 expected, observed/expected ratio (o/e) 1.05, 90% interval 0.92 to 1.21.
Homologues: Orthologues: chimpanzee TMEM45B (99% identical), macaque TMEM45B (95% identical), dog TMEM45B (84% identical), pig TMEM45B (82% identical), rabbit TMEM45B (82% identical), guinea pig TMEM45B (80% identical), mouse Tmem45b (80% identical), rat Tmem45b (78% identical), tropical clawed frog tmem45b (62% identical), zebrafish tmem45b (55% identical). Paralogues in human: TMEM45A (44% identical), TEDDM1 (18% identical).
Diseases named in the same sentence as TMEM45B in open-access papers:
TMEM45B is named in the same sentence as 27 diseases in open-access papers, as found by Europe PMC text mining. Sharing a sentence is not in itself a finding about the gene and the disease. The quoted sentences say what the papers report.
lung carcinoma (6 papers, 2014 to 2023). "Among these genes, six were already identified in the lung cancer related network of genes associated with RETC634Y signature (TMEM45B, CLDN1, TRIM29, SMUG1, SATB2, and EFNA3)." (PMID 38132167, 2023). "RNA interference of TMEM45B inhibited the migration and invasion activities in human gastric adenocarcinoma HGC-27 cells, and TMEM45B expression was associated with poor prognosis in lung cancer patients." (PMID 37367036, 2023). "TMEM45B has been shown to be associated with myeloid cells in lymph node metastasis of lung cancer." (PMID 34575089, 2021). "TMEM45B knockdown in lung cancer cell lines (A549 and H1299) also showed reduced invasive potential." (PMID 37367036, 2023). "TMEM45B knockdown in lung cancer cell lines A549 and NCI-H1975 reduced the invasive potential of these cells." (PMID 37367036, 2023). "On the other hand, TMEM45B is up-regulated in human lung cancer and promotes tumorigenicity in vivo." (PMID 30574087, 2018). "In lung cancer, TMEM45B expression has been analyzed in 110 tumor tissue samples and 35 non-tumor tissue samples." (PMID 30574087, 2018). "TMEM45B was shown to be upregulated in lung cancer and its expression was negatively correlated with overall survival." (PMID 30574087, 2018). "Invalidation of TMEM45B in A549 and NCI-H1975 cells led to the inhibition of cell proliferation, migration, and invasion highlighting its role in tumor growth in lung cancer." (PMID 30574087, 2018). "TMEM48 is such an example for lung cancer, TMEM14A for ovarian cancer and TMEM45B for lung and pancreatic cancers." (PMID 30574087, 2018). "Of them, 6 miRNAs (miR-149, miR-205, miR-375, miR-378, miR-422a and miR-708) and 9 target genes (CEACAM6, CGN, CLDN3, ABCC3, MLPH, ACSL5, TMEM45B, MUC1) were validated by quantitative PCR in an independent cohort of 41 lung cancer patients." (PMID 24625834, 2014).
gastric cancer (5 papers, 2023 to 2024). A primary or metastatic malignant neoplasm involving the stomach. "It was shown that TMEM45B was overexpressed in samples from patients with clinical gastric cancer, and its depletion in cancer cell lines using RNA interference was found to be associated with inhibition of migratory and invasive behaviors." (PMID 38850316, 2024). "For example, TMEM45B was shown to be overexpressed in clinical samples of gastric cancer." (PMID 37367036, 2023). "TMEM45B siRNA inhibited the migration and invasion phenotype of gastric cancer HGC-27 cells." (PMID 37367036, 2023). "It is a constitutively active signaling pathway in gastric cancer, its expression was investigated in HGC-27 cell, and it was observed that the knockdown of TMEM45B significantly decreased phosphorylation and activation of the JAK2 and STAT3 proteins." (PMID 37936608, 2023).
breast carcinoma (3 papers, 2023). "Similar to FGFR4/ERBB2, the overall correlation between GPR160 and TMEM45B expression in TCGA breast cancers appeared in the lower spectrum (Spearman rho = 0.35)." (PMID 37857634, 2023).
osteosarcoma (3 papers, 2023 to 2024). A usually aggressive malignant bone-forming mesenchymal neoplasm, predominantly affecting adolescents and young adults. "Furthermore, in osteosarcoma cell lines, TMEM45B deletion was associated with reduced expression of β-catenin, a transcription factor that regulates EMT gene expression." (PMID 38850316, 2024). "The silencing of TMEM45B in the U2OS cell line reduced the expression of β-catenin, cyclin D1, and c-Myc, suggesting that TMEM45B favors the osteosarcoma progression through regulation of the Wnt signaling pathway." (PMID 37936608, 2023). "Another example of TMEM45B overexpressed is in osteosarcoma cells." (PMID 37936608, 2023).
hepatocellular carcinoma (2 papers, 2023). A malignant tumor that arises from hepatocytes. "Moreover, the expression of PPP1R1B, TMEM45B, AFP, and ENPEP followed the same pattern in vitro using human hepatoma (HEPG2) and mouse liver 12 (AML12) cell lines incubated with squalene, indicating a direct effect of squalene on these expressions." (PMID 37628732, 2023).
prostate carcinoma (2 papers, 2015 to 2021). A carcinoma that arises from epithelial cells of the prostate gland. "PubMed listed n = 1 and n = 2 articles under “TMEM45B and Prostate Cancer” and “NANS and Prostate Cancer” respectively." (PMID 33578925, 2021).
atopic dermatitis (1 paper, 2025). "To explore the therapeutic potential of Tmem45b in atopic dermatitis-like itch, we conducted DNFB sensitization in C57BL/6 mice and administered intrathecal injections of either scramble siRNA or Tmem45b siRNA 2 days prior to challenge." (PMID 41451134, 2025). "Considering that Tmem45b deficiency impaired the DNFB-induced atopic dermatitis itch, Tmem45b might be involved in Nppb-mediated chronic itch rather than acute itch." (PMID 41451134, 2025).
autism (1 paper, 2022). Persistent deficits in social interaction and communication and interaction as well as a markedly restricted repertoire of activity and interest as well as repetitive patterns of behavior. "Gene TMEM45B was proved differentially expressed in white adipose tissue between autism mouse model and wild type mouse model." (PMID 35568907, 2022).
Cirrhosis (1 paper, 2023). A chronic disorder of the liver in which liver tissue becomes scarred and is partially replaced by regenerative nodules and fibrotic tissue resulting in loss of liver function. "TMEM45B is a hub gene in hepatic differentiation and is up-regulated in response to cirrhosis." (PMID 37628732, 2023).
itch (1 paper, 2025). "This contrasted with our behavioral observations, which showed Tmem45b deficiency enhanced CQ-evoked itch." (PMID 41451134, 2025).
melanoma (1 paper, 2017). A malignant, usually aggressive tumor composed of atypical, neoplastic melanocytes. "From this, we identified a panel of 6 genes, ALDH1A1, HSP90AB1, KIT, KRT16, SPRR3 and TMEM45B whose expression values discriminated metastatic from primary melanoma (87% classification accuracy)." (PMID 29229936, 2017).
neuropathy (1 paper, 2021). A disorder affecting the nervous system that manifests with pain, tingling, numbness, and/or muscle weakness. "Just 5% of silent cold cells in oxaliplatin neuropathy expressed Tmem45b." (PMID 33693512, 2021).
Obesity (1 paper, 2022). Accumulation of substantial excess body fat. "For those 12 genes, six of them (DDO, SEPT9, TMEM45B, RXRα, ZNF395 and AHRR) were previously reported to be implicated in the obesity or related diseases and the rest six were novel (PACRG, LINC00494, KLHL4, DTX1, VCX3A and VSTM1)." (PMID 35568907, 2022).
pancreatic cancers (1 paper, 2018). "In the case of pancreatic cancer, TMEM45B had also been involved in proliferation, invasion, and migration since its silencing in SW1990 and PANC-1 cell lines induced an inhibition of cell proliferation associated with cell cycle arrest." (PMID 30574087, 2018).
squamous lung cell carcinoma (1 paper, 2015). "TMEM45B down-regulation was detected in squamous lung cell carcinoma, likely due to increased expression of miRNA targeting TMEM45B gene." (PMID 26169495, 2015).
cancer (8 papers, 2014 to 2026). A tumor composed of atypical neoplastic, often pleomorphic cells that invade other tissues. "At the present time, the precise functions of ACSL5, MLPH and TMEM45B in cancer remain unknown." (PMID 24625834, 2014). "Regarding cancer stage and N-stage, there were significant correlations for TMEM206, TMEM97 (p = 0.0479, p = 0.0075), and TMEM45B (p = 0.0011), respectively." (PMID 34638224, 2021). "So far, we are observed that some TMEM proteins, such as TMEM48, TMEM45B, and TMEM168, are involved in tumor growth, proliferation, migration, and cell invasion through the Wnt/β-catenin pathway, while TMEM170B and TMEM98 act as cancer developmental inhibitors through the same pathway." (PMID 37936608, 2023).
tumor (7 papers, 2013 to 2024). "Another protein that favors tumor cells is the protein TMEM45B, recently it was shown that it is located in trans-Golgi, endosomes membrane and lysosome membrane." (PMID 37936608, 2023). "Emerging evidence has demonstrated that the TMEM family, including TMEM176A and TMEM45B, is involved in tumor progression, metastasis, and chemo-resistance." (PMID 35713314, 2022). "The expression level of TMEM45B displayed tumor stage-dependent alterations (p < 0.05)." (PMID 34456964, 2021). "The silencing of TMEM45B in the U2OS cell line decreased cell proliferation, invasion, and migration and suppressed tumor growth in vitro and in vivo." (PMID 37936608, 2023). "It has been shown that some TMEM proteins are involved in tumor growth, proliferation, migration, and cell invasion through the Wnt/ b-catenin pathway, such as TMEM48, TMEM45B, and TMEM168, whereas TMEM170B and TMEM98 act as tumor development inhibitors through the same pathway." (PMID 38850316, 2024).
TMEM45B also shares sentences with these, for which no sentence is quoted: adenocarcinoma (1 paper); cervical cancer (1); colorectal cancer (1); COVID-19 (1); gastric adenocarcinoma (1); glioblastoma multiforme (1); glioma (1); infection (1); lymph node metastasis (1); ovarian carcinoma (1).